OR10K2 (olfactory receptor family 10 subfamily K member 2)
Description:
Odorant receptor.
Synonyms: OR1-4
Tractability: Small molecule: it belongs to a druggable protein family. Antibody: UniProt places it where antibodies can reach, with medium confidence; UniProt predicts a signal peptide or a membrane-spanning region; its Gene Ontology location is reachable by antibodies, with medium confidence.
Gene: Protein-coding gene on chromosome 1 (158,418,210 to 158,426,237, reverse strand). Ensembl gene ENSG00000180708.
Subcellular location: Cell membrane
Pathways (Reactome):
Sensory Perception: Expression and translocation of olfactory receptors
Gene Ontology:
Molecular function: odorant binding; olfactory receptor activity; G protein-coupled receptor activity
Biological process: detection of chemical stimulus involved in sensory perception of smell; G protein-coupled receptor signaling pathway
Cellular component: membrane; plasma membrane
Genetic constraint (gnomAD): Loss-of-function variants: 0 observed, 0.44 expected, observed/expected ratio (o/e) 0, 90% interval 0 to 1.84. That is too few expected variants to judge how well the gene tolerates losing a copy. Missense variants: 401 observed, 382.38 expected, observed/expected ratio (o/e) 1.05, 90% interval 0.97 to 1.14. Synonymous variants: 169 observed, 151.87 expected, observed/expected ratio (o/e) 1.11, 90% interval 0.98 to 1.26.
Homologues: Orthologues: chimpanzee OR10K2 (99% identical), macaque OR10K2 (95% identical), pig OR10K2 (84% identical), dog OR10K2 (82% identical). Paralogues in human: OR10K1 (83% identical), OR10R2 (55% identical), OR10T2 (51% identical), OR10J5 (50% identical), OR10J1 (49% identical), OR10Z1 (48% identical), OR10J3 (45% identical), OR1N1 (43% identical), OR4M1 (43% identical), OR1L3 (42% identical), OR1L4 (42% identical), OR1L6 (42% identical), and 116 more.